CDK4 (cyclin dependent kinase 4)
Diseases named in the same sentence as CDK4 in open-access papers (continued):
Sharing a sentence is not in itself a finding about the gene and the disease.
breast cancer (continued). "In breast cancer, CDK4 and CDK6 are among the most well studied CDKs." (PMID 29228549, 2017). "Also, silencing of cyclin dependent kinase 4 (CDK4) in Her2+ breast cancer cells resulted in diminished levels of NEK2." (PMID 28881785, 2017). "Cyclin D1/CDK4 complexes interact and phosphorylate the scaffold protein filamin A, a member of the actin-binding protein family, thereby controlling the invasion potential of breast cancer cells." (PMID 29066743, 2017). "However, CDK4 gene regulation and its ability to respond to signals change in breast cancer cell lines, in which USF is transcriptionally inactive and CDK4 expression regulation independent of both USF and MYC." (PMID 28899340, 2017). "Here, we show that the presence or absence of the T172‐phosphorylated CDK4 form and its relative abundance varies among breast tumors according to their molecular subtypes and risk and that it predicts the response of breast cancer cell lines to PD0332991." (PMID 28566333, 2017). "However, Roniciclib affected the protein and mRNA levels of both CDK2 and CDK4 in the MCF7 breast cancer cells after a treatment for 72 h (RT-PCR P = 0.008 and 0.022, respectively)." (PMID 28246384, 2017). "HER2 and CDK4/6 are undoubted two most important biological targets for breast cancer." (PMID 28454587, 2017). "The Western blot results indicated that miR-1 overexpression led to a significant decrease in the level of CDK4 protein in the examined cells, indicating that miR-1 could target CDK4 in gastric or breast cancer cells." (PMID 28159933, 2017). "Here we report that breast cancer cells activate autophagy in response to palbociclib, and that the combination of autophagy and CDK4/6 inhibitors induces irreversible growth inhibition and senescence in vitro, and diminishes growth of cell line and patient-derived xenograft tumours in vivo." (PMID 28653662, 2017). "Furthermore, we developed a tool for predicting modification of the CDK4 profile that accurately predicted the tumor profile and sensitivity of breast cancer cell lines to PD0332991." (PMID 28566333, 2017). "Inhibition of CDK4 shows promising efficacy on advanced breast cancer." (PMID 28095789, 2017). "There are many ongoing trials that test the association of CDK4/6 inhibitors to trastuzumab, associated or not with ET in breast cancer HER-2+ (monarcHER, PATRICIA, CLEE011XUS20T, NCI-2016-00626, STU 042013-042)." (PMID 28491135, 2017). "Moreover, cyclin D1 is one of the ER transcriptional targets, thus rationalizing the use of CDK4/6 inhibitors in ERα+ breast cancer." (PMID 28454587, 2017). "The particular interest in assessing serum TK1 activity in response to CDK4/6 inhibitors stems from the known cell cycle-inhibitory properties of these agents and their importance in the management of patients with advanced HR+ breast cancer." (PMID 29162134, 2017). "PI3k/AKT/mTOR inhibitors (everolimus and temsirolimus); other mTOR inhibitors; PI3K and Akt inhibitors alone or in combination; PI3K alpha-specific BYL719 CDK4/6 inhibitors may sensitize PIK3CA mutant breast cancer to PI3K inhibitors." (PMID 28061482, 2017). "CDK4 and Cyclin D1 may be especially relevant for breast cancer, since evidence suggests that both are important oncogenic drivers for this disease." (PMID 29050219, 2017). "The present study findings may prove useful in the clinical applicability of CDK4/6 inhibitors on breast cancer patients, according to molecular profile of the tumors." (PMID 28797035, 2017). "Furthermore, with the recent introductions of CDK4/6 inhibitors for treatment of ER-positive advanced breast cancer, but with the potentially unpredictable toxicity, the combined use of tamoxifen and aspirin offers a much simpler treatment." (PMID 28415819, 2017). "However, 20% of breast cancers, including a majority of basal‐like tumors, lack CDK4 phosphorylation despite their high proliferation rate." (PMID 28566333, 2017).
breast cancer (continued). "Palbociclib and ribociclib inhibit CDK4/6 and are used for the treatment of breast cancer." (PMID 29283884, 2017). "Once adapted to a qPCR assay compatible with FFPE material and validated, our prediction tool might become clinically useful for optimizing the use of CDK4 inhibitors in the treatment of breast cancer." (PMID 28566333, 2017). "At this time, several CDK4/6 inhibitors are moving through clinical development and there will be further research into optimal combinations with other molecularly targeted agents and in other breast cancer settings." (PMID 26857361, 2016). "Furthermore, MALAT1 reversed the inhibitory effect of miR-124 on breast cancer proliferation and was involved in the cyclin-dependent kinase 4 (CDK4) expression." (PMID 27191888, 2016). "In addition, we validated that the treatment with MALAT1 and CDK4-siRNA attenuated the effect of MALAT1 on breast cancer cells proliferation." (PMID 26918449, 2016). "We further investigated whether MALAT1 increased breast cancer cell proliferation and the cell cycle by targeting CDK4." (PMID 26918449, 2016). "The data suggest that MALAT activates the CDK4/E2F1 signaling pathway in breast cancer." (PMID 26918449, 2016). "Indeed, high expression of CDK4 predicted both poor overall survival and relapse-free survival outcomes in breast cancer patients." (PMID 27759034, 2016). "Given the tumor suppressor function of CDKN2C in breast cancer, a loss-of-function of CDKN2C may have driven tumor formation in AYA02; therefore, we selected CDK4/6 inhibitors as a potential drug (palbociclib and LY2835219)." (PMID 26925973, 2016). "All together, these findings indicate that high expression of CDK4 strongly correlates with cancer stem cell-enriched subtype of breast cancer, specifically the triple-negative group and that the CDK4 kinase activity is required for maintaining the subpopulation of CD44high/CD24neg BCSC." (PMID 27759034, 2016). "Our previous studies have reported that miR-124 inhibited CDK4 expression in breast cancer cells, therefore, we testes whether MALAT1 inverted the inhibitory effect of miR-124 on CDK4 expression." (PMID 26918449, 2016). "In contrast, selective CDK4/6 inhibitors show a very favorable toxicity profile in addition to a remarkable efficacy when combined with endocrine therapy in the treatment of metastatic luminal breast cancer." (PMID 27429659, 2016). "In addition, MALAT1 reversed the inhibitory effect of miR-124 on breast cancer proliferation and was involved in the cyclin-dependent kinase 4 (CDK4) expression." (PMID 26918449, 2016). "Why is CDK4/6 inhibition reasonable in luminal breast cancer?" (PMID 27429659, 2016). "Thus, our findings provided new insights into the mechanism of breast cancer cell proliferation modulated by MALAT1-miR-124 -CDK4/E2F1 signaling pathway in the development of breast cancer." (PMID 26918449, 2016). "Nevertheless, amplification of CDK4 and cyclin D1 have been reported in upwards of 15–25 % of breast cancers, while overexpression of cyclin D1 has been reported to occur in over half of all breast cancers in some published studies." (PMID 26857361, 2016). "Moreover, we found that blocking CDK4 expression or kinase activity, using a pharmacological inhibitor prevented breast cancer stem cell self-renewal." (PMID 27759034, 2016). "The association of CDK4 gene expression with various breast cancer subtypes and clinical prognosis in human patients has not been studied." (PMID 27759034, 2016).
breast cancer (continued). "However, recent preclinical and phase I/II clinical studies using a novel, oral, reversible CDK4/6 inhibitor, palbociclib (PD-0332991), have validated the role of CDK4/6 as a potential target in estrogen receptor-positive (ER+) breast cancers." (PMID 26857361, 2016). "In tumors, CDK4 and CDK6 may be selectively required for oncogenic proliferation as described for CDK4 in breast cancer and melanoma, or CDK6 in MLL-rearranged acute myeloid leukemia (AML)." (PMID 27323399, 2016). "However, CDK4/6 inhibitors appear to require an intact pRb pathway as a mechanism of action, potentially limiting their use in a significant subset of advanced breast cancers." (PMID 27649142, 2016). "Ultimately, if validated in breast cancer, we would hypothesize that, given appropriate selection biomarkers, subgroups of patients with other tumor types may benefit from CDK4/6 inhibition." (PMID 26857361, 2016). "Therefore, the downregulation of E2F1, CDK4, cyclin D1 and cyclin D3 and upregulation of p27 and p21 in breast cancer cells likely contributed to the G1 cell cycle arrest induced by 5a." (PMID 25766325, 2015). "For example, breast cancers that have become resistant to anti-estrogen therapies (that inhibit cyclin D/CDK4 activity) present an amplification of cyclin E2, suggesting that the presence of cyclin E2 could be a potential mechanism of endocrine resistance." (PMID 25596745, 2015). "Indeed this danger was illustrated in a recent report that showed CDK4/6 inhibition protected ER(−) breast cancer cells from doxorubicin-mediated cytotoxicity." (PMID 25869441, 2015). "Importantly, we also observed synergy between Rb and FZR1 knockdown in bypassing the proliferation arrest induced by treatment of human breast cancer cells with the CDK4/6 inhibitor PD-0332991." (PMID 25562820, 2015). "Notably, these CDK4/6 inhibitors have had clinical efficacy in estrogen receptor positive breast cancer and liposarcoma." (PMID 26337082, 2015). "Therefore, here we interrogated the efficacy of CDK4/6 inhibitors in many conditions relevant to the treatment of HER2-positive breast cancer." (PMID 25221644, 2014). "Furthermore, HER2 positive breast cancer demonstrates a particular reliance on CDK4/6, which has emerged from the study of mouse models." (PMID 25221644, 2014). "Therefore, the downregulation of endogenous δEF1 in breast cancer cells is sufficient to allow inhibition of CDK4 expression." (PMID 24348783, 2014). "The CDK4/6 kinase complexes are a particularly compelling target in HER2 positive breast cancer." (PMID 25221644, 2014). "CDK4/6 inhibitors that interrupt cell cycle have therapeutic efficacy in combination with endocrine-based therapy in patients with steroid hormone receptor positive breast cancer." (PMID 23805307, 2013). "In the present work, we assessed the expression of cyclin D1, CDK4 and p16 in human invasive ductal mammary carcinoma samples, correlated the findings with the known prognostic factors for breast cancer and investigated the correlations of these three markers with survival functions." (PMID 23336272, 2013). "Because ablation of Cdk2 or Cdk4 suppresses Her2-driven mammary tumors and signals CA, the two Cdks may represent important links between CA and tumorigenesis." (PMID 23776583, 2013). "Showed that silencing CDK4 radiosensitized breast cancer cells." (PMID 23886499, 2013). "The purpose here was to correlate the immunohistochemical expression of cyclin D1, CDK4 and p16 with the main clinical prognostic factors for breast cancer: tumor stage, nodal status, tumor grade, steroid receptors (ER and PR), HER2 status and proliferation rate." (PMID 23336272, 2013). "In another study of 1,740 breast cancer patients, cyclin D1 expression was not tightly associated with proliferative genes that are regulated by the inactivation of CDK4 substrate RB." (PMID 23786849, 2013).
breast cancer (continued). "Indeed, a recent study demonstrated that luminal-type breast cancer cell lines were the most sensitive to a selective CDK4/6 inhibitor." (PMID 23390492, 2013). "Finally, a recent study investigating gene expression profiles of women with HER2-amplified breast cancer who develop early brain metastasis identified CDK4 expression as part of a 13-gene profile that predicted for early brain metastasis and death." (PMID 19874578, 2009). "Similarly, cdk4−/− mutant mice show normal proliferation in many tissues, but are resistant to ErbB-2-driven breast cancers." (PMID 19214224, 2009). "However, both the cyclin D1 nulls and the cyclin D1-KE mice are unable to support Her2/Neu induced mammary tumor formation, indicating that CDK4 activity is required for this oncogenic event in mice." (PMID 16863592, 2006). "Thus, while the relative impact of cyclin D1 mediated transcriptional control versus CDK4 modulation in breast cancer awaits further investigation, an abundance of observations support a role for cyclin D1 in transcriptional control for human tumors." (PMID 16863592, 2006). "Finally, CDK4/6 inhibitors such as Ribociclib, Palbociclib, and Abemaciclib are administered in combination with endocrine therapy as first-line therapy for treatment of advanced ER+ breast cancer." (PMID 41261233, 2026). "Together, these findings identify a distinct, non-canonical senescence phenotype associated with CDK4/6i resistance and may provide a foundation for identifying new vulnerabilities in resistant ER+ breast cancers through targeting SASP-related signaling." (PMID 41594633, 2026). "Treatment of hormone receptor (HR)-positive, HER2-negative breast cancer (HR+/HER2− BC) is limited by resistance to endocrine therapy (ET) and CDK4/6 inhibitors." (PMID 40287441, 2025). "Additionally, GPX4 and CDK4/6 inhibitors work in concert to treat breast cancer." (PMID 40969276, 2025). "Consequently, CDK9 inhibition sensitizes breast cancer to endocrine therapy, CDK4/6i, and PARPi." (PMID 40949156, 2025). "This analysis utilized a multivariable logistic regression model to evaluate factors influencing the reporting of ocular toxicity events in breast cancer patients, considering age, type of CDK4/6 inhibitor, number of concomitant medications, and whether letrozole was used concomitantly." (PMID 41282629, 2025). "Additionally, CDK4/6 plays a critical role in the luminal subtype of breast cancer." (PMID 40017494, 2025). "Therapies based on the use of cyclin-dependent kinase 4/6 inhibitor (CDK4/6i) have been developed, which are insensitive to resistance associated with mutations in the ER gene and result in prolonged progression-free survival in patients with advanced breast cancer." (PMID 41301715, 2025). "The subtype characterized by the overexpression of estrogen receptors (ER+ breast cancer) accounts for approximately 70% of all breast cancer cases and has seen significant treatment advancements due to the introduction of combined therapy of endocrine and CDK4/6 inhibitor." (PMID 40303916, 2025). "Moreover, about 4.7% of HR+/HER2− breast cancer patients exhibit Rb mutations, making CDK4/6i treatment unlikely to be effective, thus making its continuation inadvisable in these cases." (PMID 39605351, 2025). "A similar observation has been reported in palbociclib (CDK4/6 inhibitor)-treated ER + BC cells and in entinostat (histone deacetylase inhibitor)-treated in breast cancer cells, independent of ER status." (PMID 40866498, 2025). "Furthermore, studies showed that CDK4/6 inhibitors could enhance the development of memory T-cell in vivo in melanoma mouse models and in the clinical setting in breast cancer (BC) patients." (PMID 40856900, 2025).
breast cancer (continued). "We demonstrate that ErbB2 levels determine the relative contributions of CDK4-cyclin D1 and c-Myc pathways, with distinct temporal dynamics and reversibility patterns that have not been previously characterized in the context of ErbB2 heterogeneity within luminal A breast cancer." (PMID 41161384, 2025). "Considering the efficacy and good tolerability of CDK4/6i, continuing their use beyond progression, either as a rechallenge after drug holiday or by changing the partner agent, is an area of interest with clear pre-clinical rationale both in breast cancer and other solid cancers." (PMID 40427107, 2025). "Therefore, targeting MITF is a potential strategy for managing CDK4/6i-resistant breast cancer." (PMID 40244377, 2025). "By regulating the G1/S phase, cyclin‐dependent kinase 4 (CDK4) and CDK6 may participate in breast cancer cell metastasis, high Cyclin D1/CDK4 complex levels increase glioblastoma cell metastasis, and RUNX2 promotes PCa cell bone metastases and tissue invasion of C4‐2B and LNCap PCa cells." (PMID 39949984, 2025). "In endocrine-resistant HR + breast cancer, combination therapy with Fulvestrant yielded encouraging activity: partial responses were observed in both CDK4/6i-pretreated (objective response rate: 6.7%) and CDK4/6-naïve cohorts (22.7%), highlighting its potential to overcome CDK4/6 resistance." (PMID 40949156, 2025). "Despite recent treatment advances, estrogen receptor-positive (ER+) and HER2-negative (HER2−) advanced breast cancer (aBC) remains a heterogeneous disease with significant unmet need, particularly in patients relapsing early on treatment or shortly after completing adjuvant ET + CDK4/6i." (PMID 41374423, 2025). "Despite growing evidence of the potential of CDK4/6 inhibitors to slow bone progression in breast cancer patients with bone metastases, the effects of these drugs on the bone microenvironment are not fully understood, and the clinical implications of these effects remain unclear." (PMID 40005476, 2025). "We conducted a retrospective cohort study analyzing the outcomes of 95 patients with metastatic ER-positive, HER2-negative breast cancer (BC) treated with CDK4/6 inhibitors (ribociclib, palbociclib, and abemaciclib) in combination with endocrine therapy." (PMID 40244189, 2025). "This could be due to additional inhibition of CDK2 by alvocidib, as activation of the CDK2‐cyclin E pathway has been proposed as one of the resistance mechanisms to CDK4/6 inhibition and targeting CDK2 in addition to CDK4/6 overcame resistance to CDK4/6 inhibitors in breast cancer." (PMID 40415599, 2025). "Finally, we examined whether lysosomal alterations could be detected in breast cancer patients treated with CDK4/6i." (PMID 39930269, 2025). "Additionally, the phase II BYLieve study provided evidence that HR‐positive/HER2‐negative advanced breast cancer patients with PIK3CA mutations, who had previously been treated with CDK4/6i, benefited from alpelisib in combination with either aromatase inhibitors (AI) or fulvestrant." (PMID 40206206, 2025). "Over 30% of metastatic HR+ breast cancer patients develop endocrine resistance, leading to disease progression; the underlying mechanisms are complex and involve ER alterations, cross-talk with growth pathways (PI3K/AKT/mTOR, CDK4/6), and changes in the tumor microenvironment." (PMID 40427153, 2025). "Furthermore, several mechanisms have been described which contribute to resistance to CDK4/6 inhibitors in the treatment of breast cancer, which could affect the interpretation of the results of the presented studies." (PMID 40075608, 2025). "It remains unknown how the IFN pathway is activated in the CDK4/6i resistant breast cancer." (PMID 39667501, 2025).